IL6 (interleukin 6)
Diseases named in the same sentence as IL6 in open-access papers (continued):
Sharing a sentence is not in itself a finding about the gene and the disease.
Obesity (continued). "There is strong mechanistic overlap between IL-6 signaling, type 2 diabetes, and obesity, particularly through the activation of STAT3 and AR pathways." (PMID 41139205, 2025). "In patients with obstructive disorders, IL-6 levels were statistically significantly increased in children with overweight and obesity, compared with those with underweight and normal weight." (PMID 40696834, 2025). "On the other hand, as an endocrine organ, obesity secreted pro-inflammatory factors such as tumor necrosis factor α (TNF-α) and interleukin 6 (IL-6), which caused a long-term inflammatory state and affected the function of the kidney." (PMID 40230478, 2025). "Obesity is characterized by a state of chronic low-grade inflammation, with increased levels of inflammatory cytokines such as IL-6 and TNF-α." (PMID 40034545, 2025). "Interleukin‐6 (IL‐6) and tumor necrotic factor‐alpha (TNF‐α) are two cytokines associated with obesity and risk factors for adverse health." (PMID 40243109, 2025). "Despite this key limitation, we were able to validate prior studies, linking IL-6 to metabolic dysfunction, obesity, and more severe asthma." (PMID 39714726, 2025). "The parallel regulation of REG3α, IL-6, and β-defensin-2 suggests that obesity-related inflammation extends beyond adipose tissue, involving the intestinal epithelium as both a source and a target of immune signaling." (PMID 41614735, 2025). "Monocytes from individuals living with obesity exhibited an increased viral load and elevated gene expression of IL‐6 and pro‐IL‐1β compared to those from lean/overweight individuals." (PMID 40265287, 2025). "For instance, in humans, obesity is associated with chronic low-grade systemic inflammation, often marked by elevated cytokines like TNF-α, IL-6, and IL-1β." (PMID 40266905, 2025). "In people with obesity and related comorbid conditions, IL-6 secreted from adipose tissue contributes to the production of hepatic CRP and a pro-inflammatory environment." (PMID 40805975, 2025). "Since resistin is elevated in obesity, it is thought that, throughout the impact on TNF-α and IL-6, resistin can, to a certain extent, explain the association between obesity and the severity of psoriasis." (PMID 40277935, 2025). "This interaction suggests that systemic inflammation as measured by CRP is not only influenced by the presence of IL-6 but is also exacerbated in the context of obesity." (PMID 41289287, 2025). "Both among women contemplating pregnancy and pregnant participants, we found obesity associated with CRP and IL-6, which is consistent with previous findings." (PMID 40920854, 2025). "In obesity, hyperleptinemia drives IL-6 and TNF-α while reducing adiponectin, fostering insulin resistance and constraining muscle fatty acid oxidation." (PMID 41002965, 2025). "Given that obesity is a long-term inflammation potentially harming the liver, the presence of IL-1β, IL-6, and TNF-α in liver inflammation was identified using the ELISA kit." (PMID 39910919, 2025). "It was found that placental macrophages increased 2–3 times in mothers who have obesity, with an increase in cytokines such as IL-1, IL-6, TNF-α, and mRNA and protein expression." (PMID 40278381, 2025). "Obesity is characterized by chronic low-grade inflammation driven by adipose-derived cytokines/adipokines (e.g., interleukin-6 (IL-6), plasminogen activator inhibitor-1 (PAI-1), and C-reactive protein (CRP)) and immune remodeling in adipose tissue." (PMID 41373857, 2025). "High IL-6 expression correlated with age and obesity measures, while RBP4 expression showed significant associations with pT stage, lymph node involvement, TNM stage, and obesity-related parameters." (PMID 41007818, 2025). "Obesity causes adipocytes to secrete a variety of inflammatory factors, including tumor necrosis factor-α (TNF-α), interleukin-6 (IL-6), and C-reactive protein (CRP)." (PMID 38707891, 2024).
Obesity (continued). "In obesity, excess dietary fat in adipose tissue stimulates the release of immunomodulatory cytokines such as interleukin (IL)-6, leading to a state of chronic inflammation in patients." (PMID 39125976, 2024). "In obesity, adipose tissue immune cells function as the main source of increased levels of circulating IL-6." (PMID 38250713, 2024). "Despite this, there was no significant change in the inflammatory biomarker CRP, or the inflammatory cytokines IL-6 or TNFα, in agreement with other vitamin C/antioxidant intervention studies in obesity and diabetes." (PMID 38671852, 2024). "It provokes the secretion of pro-inflammatory cytokines IL-6 and IL-8 in human periodontal ligament cells (hPDLCs) via binding to the obesity-related leptin and leptin receptor b (OBRb), thereby triggering subsequent intracellular signaling cascades." (PMID 39307846, 2024). "Research has revealed that in individuals with IR (including those with obesity and T2D), the gene expression of interleukin-6 (IL-6) in skeletal muscle is enhanced, accompanied by an augmented activation of the NF-κB pathway." (PMID 39858415, 2024). "Within our analyzed studies, Takayuki and colleagues discovered that L. plantarum OLL2712 had negligible effects on obesity-related indicators, except for IL-6." (PMID 39062848, 2024). "Inflammatory markers associated with obesity, including hs-CRP, IL-6, and TNF-alpha, also demonstrated significantly higher levels in the overweight or obese group." (PMID 39200519, 2024). "Although many cytokines and chemokines are involved in obesity-induced inflammation, TNF-α, IFN-γ, IL-6, and especially IL-1β have been closely linked to systemic insulin resistance." (PMID 39606781, 2024). "In obesity, dysfunctional adipose tissue releases pro-inflammatory adipocytokines such as TNFα, IL-6, IL-1β, and free fatty acids (FFAs), which increase levels of pro-inflammatory factors." (PMID 39624218, 2024). "Obesity is known to increase proinflammatory cytokines (including interleukin-6 and tumor necrosis factor alpha in the adipose tissue) and leptin (a proinflammatory adipokine) and to decrease adiponectin, leading to dysfunction of innate immunity." (PMID 38557479, 2024). "Recent studies have also indicated that milk thistle seed cold press oil was able to improve antioxidant defences (SOD1, HO-1 and SIRT1) and attenuated inflammation markers (IL-6 and NF-κB) in a mouse model of dietary-induced obesity." (PMID 38247522, 2024). "The secreted level of IL-6 correlates with obesity, the higher the BMI the higher the IL-6 levels in the plasma." (PMID 38590830, 2024). "With worsening obesity and metabolic dysfunction, the expression of inflammatory factors IL-1β and IL-6 in human subcutaneous white adipose tissue (sub-WAT) escalated, while genes related to adipogenesis were decreased." (PMID 38672517, 2024). "This metabolically harmful NK population expands in obesity and secretes tumor necrosis factor alpha (TNFα), which ignites low-grade inflammation, increases plasma IL-6 levels, and impairs insulin sensitivity." (PMID 38474057, 2024). "In our cohort, IL-8 positively correlated with IL-6 and MCP-1 levels, and was associated with overweight, obesity and fat mass, as previously reported in other cohorts." (PMID 38892570, 2024). "In humans, elevated circulating inflammatory mediators such as IL-6 and markers such as high-sensitivity C-reactive protein correlate positively with obesity." (PMID 39188722, 2024). "Chronic low-grade inflammation, which is in part characterized by the excessive production of pro-inflammatory cytokines, such as TNF-α, IL-1β, IL-12, and IL-6 from expanded WAT, is a key driver of the metabolic dysfunction associated with obesity." (PMID 39684547, 2024). "Twelve weeks of MICT significantly reduced the levels of inflammatory factors such as interleukin 6 and tumor necrosis factor-α, increase antioxidant capacity and promoted fat metabolism in individuals with obesity." (PMID 39039573, 2024).
Obesity (continued). "The relevance of IL-6 to obesity is demonstrated by the fact that IL-6 secreted during exercise can provide energy by activating AMP-activated kinases and enhancing glucose catabolism while promoting fat oxidation and lipolysis." (PMID 39195529, 2024). "Therefore, we evaluated the IL6 secretion and expression levels after exposure of HepG2 cells to palmitic acid (PA) and high glucose (HG), which are known to cause metabolic derangement and participate in the pathogenesis of obesity, insulin resistance, and steatosis." (PMID 38892230, 2024). "The influx of macrophages into the AT contributes to obesity induced inflammation through secretion of additional inflammatory mediators including IL-6 and TNF54,56." (PMID 38800540, 2024). "In obesity, macrophages attack AT and increase the release of cytokines such as interleukin-6 (IL-6) and tumor necrosis factor-alpha (TNF-α), leading to inflammation, atherosclerosis, and vascular endothelial dysfunction." (PMID 38629096, 2024). "We detected that individuals with obesity and GI or T2D are characterized by elevated plasma levels of HbA1C and the inflammatory cytokine IL-6, by lower plasma levels of adiponectin, and by higher levels of LEPROT in their adipose tissue." (PMID 38716728, 2024). "This is characterized by the elevated levels of inflammatory cytokines like TNF-α and IL-6, which are commonly found in obesity-induced chronic inflammation." (PMID 38892561, 2024). "Circulating levels of IL-6 are markedly elevated in people with obesity, whereas long-term exercise reduces its circulating levels." (PMID 38321233, 2024). "Visceral fat acts as an active endocrine tissue, and in patients with obesity or abnormal fat distribution, the secretion of adipose-specific cytokines (leptin, IL-6, TNF-α) is increased." (PMID 39165513, 2024). "IL-6 shows an endocrine action in improving metabolic health and is positively related to obesity, insulin resistance, and type 2 diabetes." (PMID 38051471, 2024). "TNF-α also has a positive correlation with obesity and modulates leptin, as well as stimulates the production of IL-6 and CRP." (PMID 38734032, 2024). "On the other hand, a study by Matthews and co-workers demonstrated that IL-6 knock-out mice were characterized by obesity, insulin resistance and hepatosteatitis, even when fed with a standard chow diet, thus yielding contradictory results." (PMID 39404367, 2024). "Low-grade chronic inflammation is linked to obesity; this inflammation is particularly prominent in central and visceral adiposity, which is defined by elevated amounts of CRP, TNF-α, and IL-6." (PMID 38473961, 2024). "Interleukin-6 (IL-6) is another cytokine generally referred to as an obesity-related inflammatory marker." (PMID 38178093, 2024). "Higher expression of IL-6 and IL-6R were found in the adipose tissue of individuals with obesity compared to those with normal body weight or overweight." (PMID 39769504, 2024). "The same study also showed increased systemic concentration of IL-6 and/or FGF-2 in obese patients suggesting possible activation of alternative angiogenic pathways in association with obesity." (PMID 39439572, 2024). "The mean concentration of IL-6 in the group with normal body weight was 2.64 ng/mL; in the overweight group, it was 6.83 ng/mL; and in the group with obesity, the mean concentration was the highest and amounted to 8.70 ng/mL." (PMID 38786737, 2024). "Generally, the pro-inflammatory factor IL-6 regulates adipocyte production and counteracts obesity, but its role in insulin sensitivity remains controversial." (PMID 38982993, 2024). "Previous studies have observed higher concentrations of inflammatory markers such as CRP, interleukin-6, leptin, and hepcidin in women with obesity compared with normal weight." (PMID 39255312, 2024).
Obesity (continued). "Adipose tissue due to obesity can release several adipokines (including leptin, resistin, and adiponectin) as well as proinflammatory cytokines such as interleukin-1β, interleukin-6, and tumour necrosis factor-α." (PMID 38671417, 2024). "In the group of women with obesity compared to those with normal body weight, significantly higher serum levels were found for IL-6, MMP-2, and resistin." (PMID 39769504, 2024). "Obesity is characterized by low-grade chronic inflammation, as adipose tissue, an endocrine organ, secretes cytokines such as IL-6 and TNF-α." (PMID 39588046, 2024). "Nevertheless, there is evidence that obesity increases the secretion of proinflammatory cytokines from excess adiposity, especially the concentration of interleukin-6 (IL-6), which elevates the synthesis and secretion of Cp secreted by the liver." (PMID 38786759, 2024). "In obesity-induced type 2 diabetes, pro-inflammatory molecules like IL-1β, IL-6, CCL2, CCL5, and leptin play key roles in the accumulation of MDSCs in adipose tissue." (PMID 39518420, 2024). "Elevated leptin levels in obesity are associated with increased production of inflammatory cytokines, such as TNF-α and IL-6, which further contribute to chronic low-grade inflammation seen in obesity and metabolic syndrome." (PMID 39700087, 2024). "Some components of adipokines, including leptin, adiponectin, resistin, Interleukin-6 (IL-6), and Tumor Necrosis Factor-α (TNF-α), have been associated with the development of insulin resistance, obesity, and related health conditions." (PMID 39457458, 2024). "For IL-6, its serum level increases in human patients with type 2 diabetes, and obesity-based GDM mice also show renal damage, with increased blood IL-6 levels and activated MAPK signaling in the kidney." (PMID 38626157, 2024). "A clear connection exists between cholesterol levels and pro-inflammatory cytokines, such as IL-1β and IL-6, particularly among participants dealing with overweight and obesity." (PMID 38178093, 2024). "What is well established in humans is the increased presence of proinflammatory markers of inflammation such as IL-1β, TNF-α, and IL-6 within AT of individuals with obesity." (PMID 38206766, 2024). "Obesity is regarded as a chronic low-grade inflammatory state, with adipocytes secreting adipokines and inflammatory factors like IL-6 and TNF-α, which promote cellular carcinogenesis." (PMID 39867555, 2024). "In contrast, a restored level of IL-6 was found in the groups that received tart cherry juice fruits, confirming the positive role of these supplements against obesity-induced inflammation." (PMID 38671836, 2024). "Other proinflammatory markers should be assessed (IL-1, IL-6, TNFα, or Interferon) to completely characterize the picture of inflammation in patients with obesity." (PMID 40729297, 2024). "Obesity is associated with a chronic, low-grade inflammatory state, characterized by elevated levels of pro-inflammatory cytokines such as TNF-α, IL-6, and CRP." (PMID 39468643, 2024). "Research on the relationship between IL-6 levels in obesity and AD is limited.IL-6 regulates autoimmune and chronic inflammatory diseases." (PMID 39564133, 2024). "In essence, IL-6 has a therapeutic potential in the process of improving immune system, energy and glucose homeostasis in obesity through enhanced central IL-6 trans-signaling." (PMID 39376657, 2024). "In obesity, the increased secretion of inflammatory mediators, including but not limited to IL-6 and MCP-1, has been shown to contribute to impaired glucose uptake and insulin resistance." (PMID 38398822, 2024). "Daidzein, a major isoflavone from soybean, have been shown to lower IL-6 levels in a model of obesity induced neurodegeneration consisting of human fetal hypothalamic gonadotropin-releasing hormone neurons treated with palmitic acid." (PMID 39897964, 2024).
Obesity (continued). "Given that combined aerobic and resistance exercise was the most effective type of exercise to reduce IL-6 levels in women with overweight and obesity, it was intriguing that the circuit T implemented in our study resulted in increased IL-6 levels." (PMID 39640300, 2024). "We also examined the levels of inflammatory markers (TNF-α and IL-6), which were selected to assess systemic and hepatic inflammation, as both are known to play significant roles in the pathophysiology of obesity and NAFLD." (PMID 39683472, 2024). "High levels of adipokines, inflammatory modulators in obesity, are responsible for the secretion of pro-inflammatory cytokines, such as IFNγ, TNFα, IL-1β, IL-6, and IL-12." (PMID 39519568, 2024). "In models of obesity supplemented with 6-gingerol, a decrease in IL-6 concentrations in serum and adipose tissue has been evidenced, as well as in the expression at the mRNA level and the protein level of this adipokine." (PMID 39334752, 2024). "Hyper-glycolytic monocytes of people with obesity showed a normal IL-1ß, IL-6, and TNF response, whereas the IL-8 secretion in response to LPS was increased compared to monocytes of lean people." (PMID 39050851, 2024). "The administration of COST resulted in the reduction of TNF-α, IL1-β, and IL-6 levels in an obesity cardiomyopathy mouse model." (PMID 38629103, 2024). "Numerous studies have shown that peripherally secreted IL-6 traverses the blood–brain barrier and modulates food consumption, potentially mitigating obesity and obesity-related neurological disorders." (PMID 39682689, 2024). "Leptin was found to positively correlate with IL-6 and TNFα levels, as well as with clinical parameters of obesity (i.e., body mass index (BMI) and abdominal circumference)." (PMID 38247541, 2024). "It lowered colonic levels of malondialdehyde (MDA), IL-1β, and IL-6, reduced eosinophil infiltration, substance P, and inducible nitric oxide synthase (iNOS) expression indicating its inhibitory effects on obesity-induced colonic inflammation." (PMID 38629096, 2024). "Patients with psoriasis had lower VMRr compared to controls and higher average BMI, obesity rates, blood pressure values (systolic, diastolic and average) and IL-6 levels when compared to the controls." (PMID 39200092, 2024). "Proinflammatory cytokine IL-6 is upregulated in obesity and has also been shown to increase breast cancer cell migration." (PMID 39339753, 2024). "In fact, a study conducted on 25 subjects with obesity undergoing gastric bypass surgery showed that IL-6 concentrations in the portal vein were much higher than the IL-6 concentrations in the radial artery." (PMID 38455231, 2024). "The observed changes in other genes like VDR, IL-6, and NF-κB, although moderate, reinforce the idea that obesity affects multiple facets of the immune response." (PMID 39062991, 2024). "It is known that adipocyte hypertrophy and hyperplasia and increased pro-inflammatory cytokines, such as IL-6 and TNF-α, are strongly related to obesity, which is one of the causative agents of chronic inflammation." (PMID 38470620, 2024). "Evidence from mouse studies suggests that obesity-induced inflammation prompts macrophages to produce IL-6, resulting in the elevation of MDSC levels characterized by CD45+, CD11b+, Ly6G, and Ly6C+ markers." (PMID 38887300, 2024). "Adipocytes also produce excessive inflammatory cytokines such as tumor necrosis factor-alpha (TNF-a), interleukin 6 (IL6), leptin, and visfatin, which are associated with obesity, IR, or CVD." (PMID 38256617, 2024). "Notably, we observed that high saturated fat intake was associated with increased IL-6 levels (OR = 2.03, 95% CI = 1.00–4.11, p < 0.047), whereas high total fat intake was associated with increased leptin levels (OR = 2.14, 95% CI = 1.12–3.38, p < 0.021) in participants with obesity." (PMID 39700087, 2024).